CXCL8 (C-X-C motif chemokine ligand 8)
Diseases named in the same sentence as CXCL8 in open-access papers (continued):
Sharing a sentence is not in itself a finding about the gene and the disease.
acne (90 papers, 2007 to 2026). An inflammatory process of the sebaceous glands which is characterized by comedones, nodules, papules and/or pustules on the skin. "In situ studies of acne lesions have shown that the genes encoding CXCL8/IL-8, hBD-4, MMP1, MMP2, TLR2, and TLR4 are upregulated in the epidermis, and that this upregulation is associated with the activation of the NF-κB and AP-1 transcription factors." (PMID 33540667, 2021). "The ability of CBD to counteract the C. acnes-induced inflammatory response by downregulating cytokines like CXCL8, IL-1α, and IL-1β further positions it as an anti-inflammatory agent for acne." (PMID 38904694, 2024). "All these genes encode proinflammatory cytokines and chemokines previously detected in acne lesions and are linked to activation of the NF-κB pathway, inducing the upregulation of TNF-α, CXCL8/IL-8, IL-1β, CXCL1 and CXCL2." (PMID 35563458, 2022). "We found that meclozine decreased the in vitro production of CXCL8/IL-8 and IL-1β mRNA and protein in a dose-dependent manner; CXCL8/IL-8 and IL-1β are known to be involved in acne development." (PMID 35625668, 2022). "In vivo, the genes encoding CXCL8, TLR2, and β-defensin-4 have been shown to be upregulated in acne lesions, together with NF-κB and AP-1, suggesting an activation of TLR2 by P. acnes." (PMID 27902761, 2016). "C. acnes CAMP factor 2 is considered to be a virulence factor because it can induce inflammation in vivo and has been used as an antigen to elicit monoclonal antibodies, decreasing the production of CXCL8/IL-8 and IL-1β in ex vivo skin explants from patients with acne." (PMID 35563458, 2022). "The expression of CXCL10, MMP9, IL1B, CXCL8, and CXCR4 were co-regulated by IRF1, STAT1, STAT3, IKBKB, HDAC1, ETS1, and CEBPB, which were highly expressed in rosacea and acne lesions." (PMID 38321132, 2024). "Moreover, the prominent induction of genes, such as PTGS2, CXCL8, IL6, IL1B, matrix metalloproteinase 1 (MMP1) and NLRP3, even raised the possibility that EGF and PA may be involved in the pathogenesis of acne." (PMID 34025636, 2021). "Although strains different from IA1 are not typically related to acne, CAMP factor belonging to IB and II phylotypes can induce intense production of CXCL8 (IL-8) in response to TLR-2 recognition of this virulence factor by keratinocytes." (PMID 35910763, 2022). "Interestingly, the group with no sequence polymorphism (B3) corresponded to strains inducing low or moderate levels of CXCL8 production, producing a CAMP factor 1 not recognized by TLR2; all these strains were isolated from patients with moderate acne." (PMID 27902761, 2016).
lung disease (90 papers, 2004 to 2025). "Finally, the expression of the HMOX-1 and CXCL-8 genes may be of relevance in explaining some of the lung diseases associated to PM exposure." (PMID 37903867, 2023). "CXCL8 (CXC motif ligand 8, or IL-8) is the major neutrophil chemoattractant in humans, and its levels correlate with lung disease severity in sputum and BAL." (PMID 37834140, 2023). "Among the most potent neutrophil chemotactic factors produced in the airway secretions of CF patients, IL-8 (also known as CXCL8) represent one of the central mechanisms in the pathophysiology of the CF pulmonary disease." (PMID 35903151, 2022). "Strategies to inhibit aberrantly high CXCL8 expression hold therapeutic potential for CF lung disease." (PMID 26140537, 2015). "Our data have shown, that from all analyzed pro-inflammatory cytokine genes, onlyIL1B, but notTNF, CXCL8, IL6, orIL10 clearly play a crucial role in CF manifestation, determining the severe character of lung disease." (PMID 39185143, 2022).
non-small cell lung carcinoma (90 papers, 2004 to 2025). A group of at least three distinct histological types of lung cancer, including non-small cell squamous cell carcinoma, adenocarcinoma, and large cell carcinoma. "CXCL8 secreted by non-small cell lung cancer (NSCLC) cells recruits macrophages from peritumoral tissues to tumor sites and stimulates purine metabolism by increasing xanthine dehydrogenase and uric acid production, thereby promoting PD-L1 expression." (PMID 41417432, 2025). "CXC chemokines such as CXCL8 (encoding IL8) and CXCL5 are also involved in COX2-associated angiogenesis to contribute to non-small-cell lung cancer progression." (PMID 32855630, 2020). "Herein, we explored the mechanisms by which DACH1 regulated the CXCL8 in non-small cell lung cancer (NSCLC)." (PMID 29636079, 2018). "Expression of CXCL8 and its receptors correlates with angiogenesis, tumor progression, and poor survival in non-small cell lung cancer." (PMID 26087179, 2015). "Many non-small cell lung cancer cell lines produce CXCL8, the expression of which is related to angiogenesis, metastasis, and poor survival rates in many studies." (PMID 26087179, 2015). "A recent study showed that the CD56(+)CD16(−) NK subset in non-small cell lung cancer patients, which represents the predominant NK subset in tumors, was associated with VEGF, placental growth factor (PIGF), and interleukin-8 (IL-8)/CXCL8 production." (PMID 24782982, 2014). "Elevated expression of CXCL8 and its receptors has been detected in many types of cancer including prostate, colorectal, and non-small cell lung cancer." (PMID 24276377, 2013). "It has also been reported that IL-17 augments the secretion of an array of angiogenic CXC chemokines, including CXCL1, CXCL5, CXCL6, and CXCL8 by three different non-small cell lung cancer cell lines." (PMID 23665907, 2013). "Inhibition of Erk also blocked CXCL8-induced cell proliferation in non-small cell lung cancer cells." (PMID 24376747, 2013). "In addition, CXCL8 can stimulate cell proliferation in non-small cell lung cancer through EGFR transactivation." (PMID 30034618, 2018). "Our analysis was consistent with similar analysis completed in human non-small cell lung cancer in which PLAU, PLAUR, IL1R2, CD274, OSM, and CXCL8 were reported to be significantly enriched in TANs relative to circulating neutrophils." (PMID 39932553, 2025). "For instance, in non-small-cell lung cancer (NSCLC), CXCL8 triggers endothelial cell activation via its receptors CXCR1 and CXCR2, activating the PI3K and MAPK signaling pathways to promote angiogenesis." (PMID 38791448, 2024). "The contribution of ELR-CXC chemokines such as CXCL8/IL-8 and its receptors CXCR1/2 to cancer progression, including non-small cell lung cancer, has been well-documented." (PMID 26087179, 2015). "For example, the directional migration of A2056 human melanoma cells was shown by exposure of the C-X-C-type chemokine ligand (CXCL) 8, and both CXCL8 and CXCL5 expression in non-small cell lung carcinoma (NSCLC) has been correlated with tumor angiogenesis." (PMID 22952881, 2012). "Recent evidence suggests that increasing serum CXCL8 levels can predict resistance to anti-PD-1 immunotherapy in non-small-cell lung cancer patients, which has led to the development of targeted therapies directed at CXCL8 (e.g., HuMax-IL8) for the treatment of some types of cancers." (PMID 38385965, 2024). "Many non-small cell lung cancer cell lines, including H460, A549, and H358 were shown to produce CXCL8 and other ELR-CXC chemokines, while small cell lung cancers produced low or insignificant levels of CXCL8." (PMID 26087179, 2015). "In support of this notion, we did observe that non-small cell lung cancer cell lines secreted several prominent ELR-CXC chemokines, CXCL1/growth-related oncogene alpha (GROα), CXCL6/granulocyte chemotactic protein 2 (GCP-2), and CXCL8/IL-8." (PMID 26087179, 2015).
pulmonary fibrosis (90 papers, 2006 to 2025). Chronic progressive interstitial lung disorder characterized by the replacement of the lung tissue by connective tissue, leading to progressive dyspnea, respiratory failure, or right heart failure. "Furthermore, increased CXCL8 levels in airspaces may be linked to emphysematous lung changes in pulmonary fibrosis patients." (PMID 39768150, 2024). "The Net-M5 detected genes involved in lung fibrosis (CXCL8 and IL1B), VEGFA-VEGFR2 signaling (NR4A1 and CBL), and TGF-β signaling (JUNB and ATF3)." (PMID 38259488, 2023). "Genes involved in pulmonary fibrosis processes found to be upregulated in CIPF compared with healthy WHWTs in cluster M1 included FN1, SPP1, CXCL8, and PLAU (encoding plasminogen activator urokinase)." (PMID 33384697, 2020). "Among genes found to be associated with pulmonary fibrosis processes, only CCL2 and CXCL8 have already been associated with CIPF." (PMID 33384697, 2020). "We identified four overexpressed genes associated with pulmonary fibrosis processes in CIPF compared with healthy dogs in this cluster including FN1, SPP1, CXCL8, and PLAU." (PMID 33384697, 2020). "Two studies showed an increase of CXCL8 level in the BAL fluid from SSc patients that correlated with a more extensive lung fibrosis based on HRCT and inversely correlated with DLCO, FVC, and TLC, but neither study measured circulating CXCL8." (PMID 26168983, 2015). "Finally, group IV comprised several mediators of pulmonary fibrosis as IL-8/CXCL8, monocyte chemoattractant protein-1 (MCP-1)/CCL-2, monokine induced by IFN-γ (MIG)/CXCL9 and fibroblast growth factor-(FGF)-9, highly expressed in IPF patients but not in the other two groups." (PMID 38111019, 2023). "Furthermore, consistently unique cytokine expression patterns of regenerative and growth factors (CCL2, CCL11, IL6, IL12B, and CXCL8) may indicate activation of pulmonary fibrosis signaling pathways after aberrant inflammatory response." (PMID 35145507, 2021). "CXCL8 has been shown to promote angiogenesis and consequent fibrosis and additionally the levels of CXCL8 in bronchoalveolar lavage fluid were found to be increased in SSc patients with interstitial lung disease and in other fibrotic diseases, such as combined pulmonary fibrosis and emphysema." (PMID 29127442, 2018). "Levels of IL-8/CXCL8, which is a key chemotactic factor for neutrophil function, are increased in patients with pulmonary fibrosis, and the number of neutrophils in the BAL fluid correlated well with G-CSF levels, an important neutrophil growth factor." (PMID 35386685, 2022). "Our analysis showed that eight genes (CSF2, CSF3, CXCL2, CXCL8, IL1B, IL6, MMP9, and TNF) are significantly overlapping with the lung fibrosis pathway with p-value 9.35e-11." (PMID 33362771, 2020). "Studies have demonstrated an imbalance in the levels of angiogenic chemokines (ELR+ CXC chemokines [CXCL5 and CXCL8]) and angiostatic chemokines (interferon-inducible ELR- CXC chemokines [CXCL9, CXCL10, CXCL11]) in animal models of pulmonary fibrosis and lung tissue from patients with IPF." (PMID 39418259, 2024). "On the one hand, inhibition of neutrophil chemokine CXCL8 or lack of neutrophil elastase can reduce bleomycin-induced pulmonary fibrosis." (PMID 36936416, 2023). "Here, we also demonstrate that CXCL10, CCL4, CXCL8 and IL-6-producing classical, non-classical monocytes and mDC profile identify a subset of patients characterized by the presence of lung fibrosis and decreased lung function." (PMID 29127442, 2018). "Moreover, an engineered CXCL8 mutant protein (PA401), which exhibited a much higher affinity toward GAGs, showed anti-inflammatory activity in bleomycin-induced lung fibrosis in mice, resulting in a substantial reduction of transmigrated neutrophils in bronchoalveolar lavage." (PMID 35682923, 2022).
pulmonary fibrosis (continued). "Interestingly, both CXCL9 and CXCL10 but not CXCL8, exert their effects via chemokine receptor CXCR3, and CXCR3-deficient mice are known to develop progressive interstitial pulmonary fibrosis." (PMID 27127180, 2016). "Although neutrophil accumulation-inducing chemokines like IL-8 are increased in sarcoidosis, the percentage of neutrophils in the bronchoalveolar lavage remains low and is not correlated to CXCL8 or CXCL5 as in idiopathic pulmonary fibrosis." (PMID 35425769, 2022).
mastitis (89 papers, 2009 to 2025). Inflammation of breast tissue during lactation or postpartum due to an obstructed duct or infection. "CXCL8 has been shown to be upregulated in mammary infections and variability in its sequence has been associated with mastitis related traits in several independent studies." (PMID 36759924, 2023). "Interestingly, CXCL8 is preferentially targeted by bta-miR-183 hub miRNA, which could be considered as a potential therapeutic factor to counteract mastitis-induced inflammation and tissue damage caused by leukocyte influx." (PMID 37620551, 2023). "Some of the genes differentially regulated during mastitis have been reported in multiple independent expression studies (e.g., CXCL8, CXCR1, LTF, TLR4)." (PMID 36759924, 2023). "Five of the genes considered the most promising candidates (i.e., BoLA-DRB3, CXCL8, GC, NPFFR2, and STAT5A) overlap with mastitis-associated QTL (CM or SCS)." (PMID 36759924, 2023). "We have analysed the missense SNPs belonging to six genes (CXCR2, CXCL8, TLR4, BRCA1, LTF, BOLA-DRB3) and identified one marker (rs110124025) in BOLA-DRB3 that was associated with frequency of mastitis and with the number of affected quarters." (PMID 37174521, 2023). "The objective of our study was to analyse 89 missense SNPs belonging to six genes (CXCR2, CXCL8, TLR4, BRCA1, LTF, BOLA-DRB3), which were found to be associated with genetic resistance or susceptibility to mastitis." (PMID 37174521, 2023). "The case of CXCL8 is different, because the higher concentrations found in milk of E. coli than S. aureus mastitis were mirrored by a higher production by bMEC in this study." (PMID 23758654, 2013). "For example, CXCL2 and CXCL8 have been identified as the most informative genes and as candidate biomarkers of bovine mastitis, suggesting their possible effects on cow’s ability to resist mastitis." (PMID 36336691, 2022). "During E. coli mastitis, MECs lining alveoli and ducts were shown by in situ hybridization to produce CXCL8 mRNA, converging with the in vitro production of CXCL8 by MECs in response to E. coli LPS to establish that MECs are a major source of CXCL8 during E. coli mastitis." (PMID 36341445, 2022). "Experimentally induced E. coli mastitis is characterized by high concentrations of chemokines and cytokines in milk, whereas these inflammatory mediators, and in particular the chemokine CXCL8 and the cytokine TNF-α, are undetectable or in low concentrations in case of S. aureus mastitis." (PMID 23758654, 2013). "CXCL8 could therefore be considered a positional and functional candidate for mastitis resistance." (PMID 36759924, 2023). "Associations between genotypes (mainly SNPs) and mastitis-associated phenotypes (mainly SCS) have been demonstrated for 157 candidate genes in ruminants, several of which have been reported in multiple independent association studies (e.g., CXCL8, CXCR1, TLR4)." (PMID 36759924, 2023). "A study reported the up-regulation of CXCL8 and TNF-α in E. coli induced mastitis in mammary epithelial cells." (PMID 32927884, 2020). "Ours results are in keeping with published data reporting a similar increase of CXCL8 mRNA expression in peripheral blood leucocytes of SCE cows 45–55 DPP and TLR2 mRNA in cows with mastitis." (PMID 31374089, 2019). "Experimental bovine udder challenge with S. aureus isolate 1027 (subclinical mastitis) has shown that there is an immune response by one hour after pathogen challenge, with up-regulation of expression of CCL20, CXCL8, TNF and IL-6 in the teat cistern." (PMID 29705830, 2018). "Moreover, using PPI network analysis, we determined that TNF, IL-6, IL-1β, CXCL8, and ICAM1 proteins were the main targets of GYS for mastitis treatment." (PMID 38630770, 2024). "They found that three lncRNAs may affect the incidence of mastitis in dairy cows by upregulating the expression of TLR4, NOD2, CXCL8, and OAS2 genes." (PMID 39596441, 2024).
mastitis (continued). "In the present study, genes NOD2, CXCL8, OAS2, and TLR4 were differentially expressed in the blood transcriptome of subclinical mastitis cows and involved in the NOD-like receptor, Toll-like receptor pathway and were identified as key candidates for this study." (PMID 36204322, 2022). "CXCL8 is an important neutrophil chelator in BME cells, induces chemotaxis in the target cells, and has a significant change in expression levels upon TLR4 activation, which could serve as a potential biological for improving the outcome of mastitis markers." (PMID 36204322, 2022).
Hypertension (86 papers, 2009 to 2025). The presence of chronic increased pressure in the systemic arterial system. "It is worth noting that c.91 locus of the CXCL8 gene has been already associated with early-onset myocardial infarction, hypertension, chronic kidney disease, or endometrial carcinoma." (PMID 40176809, 2025). "Upon hypertension, AngII mediates continuous expression of CXCL8 through the AT1 receptor." (PMID 35668739, 2021). "CXCL8 (also known as IL-8) levels were found to be highly upregulated and significantly increased the Ca2+-dependent outflow of K+ in red blood cells in patients with hypertension Moreover, CXCL5-CXCR2 signalling mediates lens injury-induced cell infiltration through AKT activation." (PMID 35981418, 2022). "Monocyte recruitment is the key factor in the development of vascular inflammation, followed by adhesion molecules (VCAM-1 and ICAM-1), inflammatory factors (TNF-α and IL-6), and chemokines (CCL2, CXCL5, CXCL8, and CXCL10) released during hypertension." (PMID 34335249, 2021). "Meanwhile, CXCL8 promotes VSMC proliferation through the ERK pathway and increases hypertension." (PMID 35668739, 2021). "Chemokines also take part in the pathogenesis of hypertension, including monocyte chemoattractant protein-1 (MCP-1, CCL2), Gro-α (growth-related oncogene), interferon-inducible protein (IP-10, CXCL10) interleukin-8 (IL-8; CXCL8), CXCL1/RaNTeS (CCL5)/CCR5 and fractalkine (FKN aka CX3CL1)/CX3CR1." (PMID 32848763, 2020). "Therefore, it has been suggested that IL-8/CXCL8 is also involved in the pathogenesis and maintenance of hypertensive vascular wall formation in hypertension." (PMID 20107546, 2009). "However, after adjusting for age, hypertension, atrial fibrillation, NIHSS admission score, right-sided lesion, and pre-stroke dependency in a multivariate analysis, only higher levels of CXCL10, CXCL9, and CXCL8 remained independent predictors of outcome." (PMID 38861234, 2025). "While prior studies have focused on tear cytokines in diabetic retinopathy, our study identified elevated tear cytokines (IL-6, CXCL8, IL-15, CCL5, and VEGF) in diabetic patients without diagnosed retinopathy, persisting after controlling for age, hypertension, and dyslipidemia." (PMID 41030257, 2025).